HOXC8 (homeobox C8)
Description:
Sequence-specific transcription factor which is part of a developmental regulatory system that provides cells with specific positional identities on the anterior-posterior axis.
Synonyms: HOX3A; HOX3
Tractability: No criterion of Open Targets' tractability assessment is met for any kind of drug.
Gene: Protein-coding gene on chromosome 12 (54,008,985 to 54,012,769, forward strand). Ensembl gene ENSG00000037965.
Subcellular location: Nucleus
Subcellular location (Human Protein Atlas): Microtubules; Nucleoplasm
Pathways (Reactome):
Cell-Cell communication: Regulation of CDH11 gene transcription
Gene Ontology:
Molecular function: protein binding; sequence-specific double-stranded DNA binding; DNA-binding transcription factor activity, RNA polymerase II-specific; RNA polymerase II transcription regulatory region sequence-specific DNA binding; DNA binding; DNA-binding transcription factor activity
Biological process: regulation of transcription by RNA polymerase II; regulation of DNA-templated transcription
Cellular component: nucleoplasm; chromatin; nucleus
Genetic constraint (gnomAD): Loss-of-function variants: 14 observed, 25.1 expected, observed/expected ratio (o/e) 0.56, 90% interval 0.37 to 0.87. The upper end of that interval is the gene's LOEUF score, 0.87, which puts it in group 3 of 6, group 1 being the genes least tolerant of losing a copy. Missense variants: 316 observed, 320.97 expected, observed/expected ratio (o/e) 0.98, 90% interval 0.9 to 1.08. Synonymous variants: 144 observed, 135.58 expected, observed/expected ratio (o/e) 1.06, 90% interval 0.93 to 1.22.
Homologues: Orthologues: chimpanzee HOXC8 (99% identical), macaque HOXC8 (99% identical), mouse Hoxc8 (99% identical), pig HOXC8 (99% identical), rabbit HOXC8 (99% identical), rat Hoxc8 (99% identical), dog HOXC8 (98% identical), tropical clawed frog hoxc8 (91% identical), zebrafish hoxc8a (85% identical), guinea pig HOXC8 (82% identical). Paralogues in human: HOXD8 (62% identical), HOXB8 (61% identical), HOXA7 (34% identical), HOXB6 (34% identical), HOXB7 (34% identical), HOXA6 (32% identical), HOXC6 (32% identical), HOXB5 (32% identical), HOXA5 (30% identical), HOXD4 (29% identical), HOXB4 (28% identical), HOXC4 (27% identical), and 30 more.
Diseases named in the same sentence as HOXC8 in open-access papers:
HOXC8 is named in the same sentence as 65 diseases in open-access papers, as found by Europe PMC text mining. Sharing a sentence is not in itself a finding about the gene and the disease. The quoted sentences say what the papers report.
breast cancer (24 papers, 2014 to 2025). A primary or metastatic malignant neoplasm involving the breast. "More importantly, high expression of CDH11, ILF3 and HOXC8 is linked to poor distant metastasis-free survival (DMFS) for breast cancer patients." (PMID 29296180, 2017). "Overall, these results indicated that CDH11, ILF3 and HOXC8 were highly upregulated in the advanced stages of breast cancer, and high expression of CDH11, ILF3 and HOXC8 were associated with a poor DMSF for breast cancer patients." (PMID 29296180, 2017). "Previously we demonstrated that high expression of HOXC8 was significantly associated with low recurrence-free survival rate of breast cancer patients, so we evaluated the correlation between embigin expression and breast tumor recurrence." (PMID 26090721, 2015). "CDH11 over-expression is associated with poor recurrence-free survival in breast cancer, and depletion of its transcription factor HOXC8 resulted in fewer metastases in animal models." (PMID 25686838, 2015). "A critical role of HOXC8 in tumor progression and development is implicated by the observation that the expression of HOXC8 is deregulated in various cancer types including prostate, cervical and breast cancer." (PMID 24810778, 2014). "Since CDH11 is expressed only in invasive breast cancer cells and HOXC8 acts as either a transcriptional activator or repressor, we speculated that HOXC8 associated with other proteins to activate CDH11 transcription in breast cancer cells." (PMID 29296180, 2017). "In conclusion, this study demonstrates that embigin is transcriptionally regulated by HOXC8 protein and its low/loss expression may play an important role in the progression of breast cancers." (PMID 26090721, 2015). "Kaplan-Meier survival analyses showed that both high CDH11 and ILF3 were significantly associated with a poor distant metastasis-free survival (DMSF) rate for breast cancer patients (P = 0.014 and 0.023, respectively), and high expression of HOXC8 may also be associated with poor DMSF (P = 0.064)." (PMID 29296180, 2017). "In our previous study, we showed evidences that HOXC8 functions as transcription activator to induce cadherin-11 expression in breast cancer cells, which suggested that HOXC8 may associate with different co-factors to activate or inhibit its target genes transcription in breast cancer cells." (PMID 26090721, 2015). "In this study, we show that HOXC8 binds to the embigin promoter and transcriptionally inhibits embigin expression, and loss of embigin expression enhances proliferation, anchorage-independent cell growth, and migration of breast cancer cells and normal breast cell MCF10A." (PMID 26090721, 2015). "We previously revealed that the ratio of miR-196 to HOXC8 mRNA is correlated with metastatic behaviors in breast cancer." (PMID 40701951, 2025). "In silico analysis using TCGA breast cancer patient data confirmed the significant increase in DNA methylation at the HOXC8 promoter region in breast cancer tumors compared to normal tissues." (PMID 39858044, 2025). "Later studies showed that HOXC8 is involved in breast cancer progression by either transcriptionally upregulating cadherin-11 expression or acting as a transcriptional repressor of the tumor suppressor Embigin." (PMID 40701951, 2025). "Previously, we have shown that HOXC8 acts as a transcriptional activator to promote expression of CDH11 in basal-like breast cancer cells leading to increased anchorage-independent cell growth, migration and invasion." (PMID 40701951, 2025). "Breast CSCs with HOXC8 overexpression were more sensitive to chemotherapy agents, had reduced self-renewal capacity, and had reduced anchorage independence, all indicating the role of HOXC8 in breast cancer initiation." (PMID 39858044, 2025). "Meanwhile, HOXC8 was also involved in regulating the development and progression of various human malignancies, such as gastric and breast cancer." (PMID 36421849, 2022).
breast cancer (continued). "Another oncogenic driver gene homeobox C8 (Hoxc8) has also been reported as an important regulator of the formation of stem cells and can act as a regulator of breast cancer cells differentiation." (PMID 33898430, 2021). "The role of HOXC8 in breast cancer, in which silencing seems to interfere with the self-renewal, differentiation and transformation of breast cancer stem cells, is also instigated by promoter hypermethylation." (PMID 32635388, 2020). "In our previous studies, we reported that HOXC8 was upregulated in breast cancer cells and ectopic expression of HOXC8 promoted breast cancer migration and metastasis." (PMID 29367650, 2018). "Taken together, these data indicated that ILF3 interacted with HOXC8 in CDH11-expressing breast cancer cell lines." (PMID 29296180, 2017). "Using co-immunoprecipitation (Co-IP) and mass spectrometry analyses (MS), we observed that ILF3 co-purified with HOXC8 and co-localized with HOXC8 in the nuclei of breast cancer cells." (PMID 29296180, 2017). "In summary, all our data together demonstrated that LF3 and HOXC8 co-regulated CDH11 transcription in breast cancer cells and promoted the proliferation and migration of breast cancer cells by facilitating CDH11 expression in breast cancer cells." (PMID 29296180, 2017). "Here, we report that interleukin enhancer binding factor 3 (ILF3) interacts with Homeobox C8 (HOXC8) to activate CDH11 transcription in breast cancer cells." (PMID 29296180, 2017). "Downregulation of HOXC8 in breast cancer was also found by meta-analysis of breast cancer data from large cohort studies." (PMID 28202042, 2017). "Taken together, our study demonstrated that ILF3 was involved in HOXC8-regulated CDH11 transcription in breast cancer cells." (PMID 29296180, 2017). "We previously reported that Homeobox C8 (HOXC8) acts as a transcription factor to induce CDH11 expression in breast cancer cells." (PMID 29296180, 2017). "Together, these observations indicated that ILF3 and HOXC8 formed a protein complex to co-activate CDH11 transcription in breast cancer cells." (PMID 29296180, 2017). "Previous studies have reported an increased expression of HOXC8 during breast cancer progression that can induce metastasis through direct regulation of CDH11 and EMB genes." (PMID 28202042, 2017). "Using co-immunoprecipitation and mass spectrometry analyses, ILF3 is shown to interact with HOXC8 in breast cancer cells." (PMID 29296180, 2017). "Of the genes commonly altered across different breast cancer molecular subtypes, HOXC8 was chosen as a putative novel tumour suppressor gene." (PMID 28202042, 2017). "In the Co-IP experiments, we found that both NF90a/b and NF110a/b were significantly enriched in the HOXC8 immunoprecipitates, indicating that both NF90 and NF110 interacted with HOXC8 in breast cancer cells." (PMID 29296180, 2017). "Taken together, our study points to an important role of homeobox genes in breast cancer stem/progenitor cell function and establishes HOXC8 as a suppressor of stemness and transformation in the mammary gland lineage." (PMID 28202042, 2017). "HOXC8 knockdown mediated inhibition on breast cancer cell growth and migration can be reversed largely by removal of embigin protein expression, indicating the functional linking between embigin and HOXC8 in breast tumorigenesis." (PMID 26090721, 2015). "Taken together, these results show that inhibitory effects of embigin on cell proliferation, anchorage-independent growth and cell migration are functionally regulated, at least in part, by HOXC8 protein in breast cancer cells." (PMID 26090721, 2015). "It has been reported that HOXC8 takes part in a number of genes regulation in mouse fibroblasts, and our previous study also showed that HOXC8 promotes breast cancer cell migration and metastasis through activating cadherin-11 transcription." (PMID 26090721, 2015).
breast cancer (continued). "To determine the roles of HOXC8, we ectopically expressed HOXC8, or depleted HOXC8 expression by shRNA knockdown in breast cancer MDA-MB-231 and MCF7 cell lines." (PMID 26090721, 2015). "In this study, we show that embigin is transcriptionally regulated by Homeobox C8 (HOXC8) in breast cancer cells and embigin expression suppresses breast tumorigenesis." (PMID 26090721, 2015). "Taken together, our results showed that embigin is transcriptionally regulated by HOXC8 protein, and plays a suppressive role in breast cancer progression." (PMID 26090721, 2015). "Taken together, these data show that HOXC8 is involved in regulation of embigin expression in breast cancer cells." (PMID 26090721, 2015). "Previously we reported that HOXC8 plays an important role in breast tumorigenesis, and acts as a transcription factor in cadherin-11 transcription in breast cancer cells." (PMID 26090721, 2015). "Together, our study suggests that HOXC8 promotes breast tumorigenesis by maintaining high level of CDH11 expression in breast cancer cells." (PMID 24810778, 2014). "Both high HOXC8 and CDH11 expression were significantly associated with poor recurrence-free survival rate of breast cancer patients (P = 0.002 and 0.041 respectively)." (PMID 24810778, 2014). "To understand the molecular mechanism mediating CDH11 expression in invasive breast cancer cells, we showed that knockdown of HOXC8 led to the reduction of CDH11 expression." (PMID 24810778, 2014). "Here, we show that CDH11 is transcriptionally controlled by homeobox C8 (HOXC8) in human breast cancer cells." (PMID 24810778, 2014). "We showed that HOXC8 level is elevated in invasive/metastatic breast tumor cell lines and its presence is required for breast cancer cell migration and metastasis." (PMID 24810778, 2014). "To further define the role of HOXC8 in CDH11 expression, we ectopically expressed HOXC8 in breast cancer MDA-MB-231 and Hs578T cell lines." (PMID 24810778, 2014). "This possibility is supported by our early finding that the depletion of HOXC8 diminishes breast cancer cell migration, invasion and metastasis." (PMID 24810778, 2014). "To do so, we first assessed the association between HOXC8 and CDH11 mRNA expression in breast tumors using microarray data of 414 breast cancer patients obtained from the Gene Expression Omnibus (GEO)." (PMID 24810778, 2014). "Here, we show that enforcing HOXC8 expression significantly upregulates CDH11 expression in breast cancer cells." (PMID 24810778, 2014). "Our reasoning is apparently supported by the observation that ectopically expressing CDH11 restored various tumorigenic events diminished in HOXC8-knockdown breast cancer cells." (PMID 24810778, 2014). "Recent studies have found the level of HOXC8 in transitional breast cancer cells significantly increases, suggesting that the presence of HOXC8 may affect the migration of breast cancer cells." (PMID 33442417, 2021). "Moreover, miR-196b promotes cell migration and invasion by targeting FOXP2 in hepatocellular carcinoma and regulates self-renewal, differentiation, and transformation by targeting HOXC8 in breast cancer stem cells." (PMID 32258122, 2020). "Lastly, we showed that CDH11, ILF3 and HOXC8 were expressed at statistically higher levels in breast cancer specimens than in normal breast tissues, and the association of CDH11, ILF3 and HOXC8 was linked to poor distant metastasis-free survival for breast cancer patients." (PMID 29296180, 2017). "Moreover, expression of CDH11, ILF3 and HOXC8 showed a significant tendency toward co-occurrence among these breast cancer samples." (PMID 29296180, 2017). "Regulation of HOXC8 via miRNA 196 has been reported in breast cancer whereby the ration of miR196 and HOXC8 correlates with cell migration and metastasis and methylation of the HOXC8 promoter can induce gene silencing by inducing polymerase II stalling during transcription." (PMID 28202042, 2017).
breast cancer (continued). "As a laboratory study may not always recapitulate the clinical malignancy, we performed immunohistochemistry staining (IHC) to examine CDH11, ILF3 and HOXC8 protein levels in breast cancer specimens and normal breast tissues." (PMID 29296180, 2017). "To further clarify the roles of HOXC8 in regulation of CDH11 transcription in breast cancer cells, we immunoprecipitated HOXC8 protein complexes and observed that interleukin enhancer-binding factor 3 (ILF3) co-precipitated with the HOXC8 protein in this study." (PMID 29296180, 2017). "Moreover, immunohistochemistry (IHC) shows that expression of CDH11, ILF3 and HOXC8 are all upregulated in breast cancer specimens compared to normal breast tissues." (PMID 29296180, 2017). "We initially demonstrated that HOXC8 functions as a transcription factor to inhibit embigin transcription, and embigin knockdown enhances the proliferation, anchorage-independent growth and migration of breast cancer cells and normal breast cells." (PMID 26090721, 2015). "Previously we reported that HOXC8 mediates proliferation, migration and metastasis of breast cancer cells, it is interesting to explore whether HOXC8 affects these behaviors by regulating embigin transcription." (PMID 26090721, 2015). "Based on these findings, we hypothesize that HOXC8 regulates various genes transcription in breast cancer development, which includes activating cadherin-11 and inhibiting embigin transcription in breast cancer cells." (PMID 26090721, 2015). "Previously we reported that HOXC8 plays an important role in promoting breast cancer development, correlating with other reports that HOXC8 expression is deregulated in several cancers, such as cervical cancer, prostate cancer, esophageal cancer, and pancreatic cancer, etc." (PMID 26090721, 2015). "Among those genes, we are interested in examining whether HOXC8 is involved in regulating embigin expression in breast cancer cells." (PMID 26090721, 2015). "As laboratory study may not always recapitulate clinical breast malignancy, we explored the potential clinical relevance of HOXC8/CDH11 expression in human breast cancer." (PMID 24810778, 2014). "Our early study demonstrate that HOXC8 is required for breast cancer cell migration and metastasis." (PMID 24810778, 2014). "To functionally link HOXC8 to CDH11 in breast tumorigenesis, we show that the depletion of HOXC8 leads to the significant reduction in anchorage-independent cell growth, cell migration/invasion and spontaneous metastasis of breast cancer MDA-MB-231 and Hs578T cells." (PMID 24810778, 2014). "Given the importance of CDH11 in breast cancer cell migration and metastasis, we speculated that HOXC8 might impact breast tumorigenesis by serving as a CDH11 transcription factor." (PMID 24810778, 2014). "Three members of the miR-196 family where the resulting miR-196a-3p belongs – miR-196a-1, miR-196a-2, and miR-196b – could suppress breast cancer cell migration and metastasis by inhibiting HOXC8, which promotes tumorigenesis by regulating the expression of cadherin-11 in breast cancer." (PMID 34512726, 2021). "However, another study revealed that ectopic expression of miR-196b-5p abrogated invasion in vitro and in vivo spontaneous metastasis of breast cancer cells via targeting transcription factor HOXC8, indicating that miR-196b-5p is a potent metastasis suppressors." (PMID 28591704, 2017). "Importantly, the expression levels of CDH11, ILF3 and HOXC8 are elevated in the advanced stages of breast cancer, and high expression of CDH11, ILF3 and HOXC8 is associated with poor distant metastasis-free survival (DMFS) for breast cancer patients." (PMID 29296180, 2017). "Therefore, it is our interest to investigate whether HOXC8 could function as the embigin transcription factor in breast cancer cells." (PMID 26090721, 2015).